MTOR (mechanistic target of rapamycin kinase)
Diseases named in the same sentence as MTOR in open-access papers (continued):
Sharing a sentence is not in itself a finding about the gene and the disease.
tumor (continued). "It is showed that circRNAs participated in tumor progression by activating multiple signal pathways such as β-catenin signaling, AMPK-mTOR pathway, TGF-β pathway, PI3K/AKT/mTOR signaling pathway." (PMID 36514094, 2022). "We found that SCT treatment significantly induced the phosphorylation of mTOR, and its downstream substrates p70S6K and 4E‐BP1 in MCF7 and HCT116 cells, indicating activation of mTOR pathway in tumor cells after citrate treatment." (PMID 34747157, 2022). "In the process of tumor development, there are also many tumor suppressors, which inhibit the proliferation of cells through inactivating PI3K/Akt/mTOR pathway." (PMID 35392233, 2022). "Aside from the direct anti-proliferative effect on tumor cells, increasing evidence supports the immune-modulatory effect of PI3K/AKT/mTOR and MAPK/MEK/ERK inhibitors, making their adjuvant potential with immunotherapy an intriguing therapeutic option." (PMID 35806358, 2022). "For example, in various tumor cell types, flavanone naringenin has a strong inhibitory effect on the PI3k/AKT/mTOR signaling pathway." (PMID 35884991, 2022). "A PI3K/mTOR inhibitor combined with ABT-737 and tamoxifen markedly attenuated tumor growth in these tumors." (PMID 35053443, 2022). "One study showed that 4-chloro fascaplysin, a marine sponge alkaloid derivative, inhibited tumour growth and VEGF-mediated angiogenesis by disrupting the PI3K/Akt/mTOR signalling cascade." (PMID 36474188, 2022). "In the tumor microenvironment, the PI3K/AKT/mTOR pathway plays an important role in promoting the proliferation and metastasis of tumor while strongly inhibiting the antitumor immune response." (PMID 36189258, 2022). "The inhibitory effect of PTS on the in-tumor mTOR pathway resulted in the downregulation of TGF-β, CD44, VEGF, and EGFR, which would have had the effect of retarding tumor-cell migration and invasion, thus reducing the potential risk of metastasis." (PMID 36077992, 2022). "Calorie restriction and fasting have long been recognized as limiting tumor growth in animal studies and it has been proposed that this is due to reduced insulin-mediated PI3K/Akt/mTOR signaling." (PMID 36046843, 2022). "While intracranial CW implantation appeared to control local tumor recurrence, TMZ administration was used to synergistically resensitize mTOR suppression in order to modulate MGMT protein expression." (PMID 35646111, 2022). "The network of related pathways showed that the DREAM complex was significantly involved in tumor-related signaling pathways, including TSC/mTOR, RTK, RAS/MAPK, PI3K/AKT, Hormone ER, Hormone AR, EMT, DNA damage response, cell cycle, and apoptosis pathways." (PMID 35664326, 2022). "PI3K/AKT/mTOR signaling pathway is usually activated in HCC patients and closely related to the anti-tumor effect of LA." (PMID 36713494, 2022). "Studies on other types of inhibitors, such as ATP-competitive mTOR inhibitors and mTOR/PI3K dual inhibitors, have also shown tumor growth inhibition effects against CRC cell lines and xenograft models." (PMID 35883111, 2022). "The majority of the biomarkers examined in this analysis are involved in tumor cell proliferation, HER2, EGFR, cyclin D, KI67 and MTOR were among the most frequently reported in literature found by the authors." (PMID 35246597, 2022). "In bladder cancer, PKM2 interacts with SREBP-1c through the regulation of the Akt/mTOR signaling pathway, which in turn activates FASN transcription for tumor growth." (PMID 35912181, 2022). "FBXW7 reshapes the proliferative niches of tumor cells through ubiquitinating and degrading several crucial signal molecules, such as c-MYC, c-Jun, phosphatidylinositol 3-kinase (PI3K)/AKT, mTOR, Notch, as well as JAK/STAT signaling pathway." (PMID 35515121, 2022). "Tannins play important roles by regulating multiple tumor signaling pathways, including the JAK/STAT, RAS/RAF/mTOR, TGF-β1/TGF-β1R, VEGF/VEGFR and CXCL12/CXCR4 axes." (PMID 36278230, 2022).
tumor (continued). "Subgroup B was significantly more active in pathways that facilitate tumor progressions, such as angiogenesis, MYC-mediated targets, and the mTOR signaling pathway." (PMID 36003780, 2022). "By activating AMPK and inhibiting mTOR and HIF-1α, Metformin in combination with 5-Fluorouracil increases the tumor response to chemotherapy by regulating the enzymes involved in the Warburg effect in human oral squamous cell carcinoma." (PMID 36568220, 2022). "Nevertheless, insulin appears to impact tumor growth in certain contexts, which is driven by the PI3K (Phosphoinositide 3-kinase) and mTOR (mammalian target of rapamycin) signaling pathway." (PMID 36230918, 2022). "TB was found to suppress tumor cell proliferation while promoting apoptosis, through its suppression on the PI3K/Akt/mTOR pathway." (PMID 36139789, 2022). "LncRNA NBR2 inhibits tumor development by regulating autophagy in HCC, and lncRNA CASC9 activates autophagy-mediated cell death by AKT/mTOR pathway." (PMID 36072894, 2022). "Even though FLCN’s function is not fully understood, it has been suggested that FLCN acts as a tumour suppressor gene interacting with FNIP1 and FNIP2 proteins, thus playing a key role in mammalian target of rapamycin (mTOR) signalling pathway." (PMID 35176117, 2022). "PTEN is an important tumor suppressor that opposes phosphoinositide 3-kinase (PI3K) function, leading to inactivation of AKT and mammalian target of rapamycin (mTOR) signaling." (PMID 35954222, 2022). "PI3K/AKT, mTOR, and MAPK signaling pathways play important roles in MDSC functional polarization in tumor." (PMID 35785030, 2022). "mTOR signaling pathway affects tumor proliferation, metastasis, and drug resistance, and MALAT1 mediates the mTOR pathway in multiple cancers." (PMID 35557985, 2022). "In HER2 BC, autophagy has been considered a tumor-inhibiting process because of the activation of several oncoproteins involved in HER2 signaling, such as both mTOR and AKT, which provokes autophagy inhibition." (PMID 36139701, 2022). "This was associated with decreased expression of the SMYD2 protein substrates EZH2, p65, p-mTOR, and p-MAPK in OC-PF-treated primary tumor samples compared to in the placebo control-treated animal tumors." (PMID 35884603, 2022). "Compared with the adjacent tissues, MTERF1 was highly expressed, p-AMPK was suppressed, p-mTOR was increased, and the downstream effector proteins p-mTOR, P70S6K, and 4E-BP1 were phosphorylated in tumor tissues." (PMID 36293209, 2022). "It is confirmed that everolimus (an inhibitor of mTOR) can inhibit the growth of ESCC in both cell lines and transplanted tumor models." (PMID 35574327, 2022). "In the tumor environment, PI3Kγ protein expression inhibits NF-κB activity through AKT and mTOR while stimulating C/EBPβ activation in macrophages, resulting in suppression of antitumor immune effects." (PMID 36313041, 2022). "EZH2 increases H3K27me3 in the promoter of PTEN thus silencing PTEN and activating the threonine protein kinase B (AKT)/mTOR pathway, promoting GBM tumor cell proliferation and metastasis." (PMID 35572545, 2022). "Salmonella invasion in a tumor can downregulate the expression of HIF-1α and VEGF, and inhibits tumor angiogenesis via the AKT/mTOR pathway." (PMID 36297535, 2022). "This evidence demonstrates that there is a correlation between the development of malignant phenotypes in tumor cells and activation of the PI3K/AKT/mTOR pathway." (PMID 35412944, 2022).
tumor (continued). "Of these genes, one tumor suppressor, PIK3IP1, was particularly notable, as it attenuates PI3K/AKT/mTOR signaling through a direct inhibition of PIK3CA/p110α." (PMID 35852858, 2022). "Strategies for modulating mTOR signaling also can serve to enhance fitness and cytotoxicity of TCR-T while concomitantly reducing tumor cell growth." (PMID 36479131, 2022). "As described in recent studies, hypoxia induces Akt accumulation in mitochondria, which in turn stimulates tumor metabolic reprogramming-related factors, such as HIF1-2α through PI3K/Akt/mTOR signal pathway activation and LKB1/AMPK and cMYC downregulation." (PMID 35328408, 2022). "The results suggest that CDK1 was positively correlated with PI3K/Akt/mTOR pathway, cellular hypoxia response, EMT related genes, G2M checkpoint, and tumor proliferation, while negatively correlated with angiogenesis." (PMID 36078096, 2022). "Systemic inflammation promotes the release of fibrinogen, which promotes tumor cell proliferation and metastasis by participating in extracellular matrix formation and inducing epithelial–mesenchymal transition via the p-AKT/p-mTOR pathway and IL-6 synthesis." (PMID 36387142, 2022). "For example, mTOR is a major direct regulator of the Warburg effect, while HIF1α, a downstream mTOR target, is highly expressed and synergizes with c-Myc-hnRNP splicing modulators to enhance PKM2 expression, which, in turn, promotes tumor progression." (PMID 36588722, 2022). "Studies have shown that bufalin can target the mTOR/VEGF signaling pathway, affecting the tumor vascular microenvironment and improving the anti-angiogenic effect." (PMID 35433834, 2022). "Oncogenic signatures manifested PDG, MTOR, and PETEN pathway as the enriched signature in NT tumor cells." (PMID 34026600, 2021). "KEGG pathway enrichment analysis indicated that those autophagy-related lncRNAs were involved in multiple tumor progressions and signaling pathways such as NOD-like receptor signaling pathway and mTOR signaling pathway." (PMID 34040677, 2021). "PRAS40, when dephosphorylated, inhibits mTOR signaling, consequently decreasing ribosomal transcription via affecting the activation of 4E-BP1 and P70S6k, both of which play roles in tumour angiogenesis." (PMID 34066403, 2021). "In BLCA, smoking induces tumor growth and mTOR inhibitor resistance through activation of the PI3K/Akt/mTOR signaling pathway." (PMID 34796198, 2021). "Overexpression of MIA enhances tumor cell survival and promotes activation of the PI3K/mTOR signaling pathway." (PMID 34441956, 2021). "Our data show that Fr-BuVt can suppress mTOR, ERK, NFκB and PCNA expressions in Ehrlich carcinoma-bearing mice tumor." (PMID 33413302, 2021). "In HCC, several oncogenic signal transduction pathways, such as MAPK, PI3K/AKT/mTOR, JAK/STAT, cMET, IGF and NF-κB, were found to play critical roles in tumor initiation and progression." (PMID 34510031, 2021). "Low levels of GABARAP increased p-AKT and p-mTOR levels, and a specific AKT pathway inhibitor reversed the downregulation of GABARAP-induced tumor progression." (PMID 33591943, 2021). "Blocking mTOR activity by rapamycin (sirolimus) inhibited cell growth in cell culture and tumor growth in a KSHV related mouse model, whereas overstimulation of the mTOR pathway resulted in the opposite, showing that this pathway is important for KSHV." (PMID 34578378, 2021). "Opportunities also exist to leverage known or novel drug combinations targeting tumor cell-specific vulnerabilities elicited by WNT inhibitors, including MEK or MTOR inhibition in combination with PORCNi." (PMID 33996827, 2021). "The HGF/c-MET signaling pathway regulates downstream PI3K/Akt/mTOR, Ras/MAPK, and JAK/STAT signaling pathways, which are important in regulating tumor cell growth, migration, and invasion." (PMID 34408780, 2021).
tumor (continued). "Angiogenesis inhibitors target tumor and stromal cells hampering the expression of pro-angiogenic factors such as EGF, VEGF, and their receptors (EGFR, VEGFR), or interfering with the mammalian target of rapamycin (mTOR) signaling pathway." (PMID 34885006, 2021). "The PI3K/AKT/mTOR signaling pathway was shown to be significantly upregulated and PTEN was largely downregulated in tumor tissue." (PMID 33572326, 2021). "Tumour subtype specificity on Wnt, Notch, VEGFA-VEGFR2 and PI3K-Akt-mTOR in TN and cytokines in ER+ were observed." (PMID 34193143, 2021). "It has been reported that TAMs reside in hypoxic tumor regions and significantly upregulate the expression of regulated in development and DNA damage responses 1 (REDD1), which inhibits mammalian target of rapamycin (mTOR) activity." (PMID 33514004, 2021). "Both the inhibitors showed mutant-selective inhibition of tumor growth with a marked effect on K-Ras (mutant-G12C)–ERK–MAPK and mTOR–S6K kinase pathways." (PMID 34204435, 2021). "The downregulation of LINC01419 suppresses tumor growth and promotes autophagy through the inactivation of the PI3K/Akt1/mTOR pathway in GC (Wang L.-L." (PMID 34805143, 2021). "The phosphatase and tensin homologue (PTEN), a well-characterized tumor suppressor, negatively regulates PI3K/Akt/mTOR signaling pathway." (PMID 35250965, 2021). "It was revealed that GAS5 was capable of repressing tumour cell viability and proliferation by blocking the protein kinase B (AKT)/mammalian target of rapamycin (mTOR) signalling pathway." (PMID 33968736, 2021). "In conclusion, ADGRG1 mediates tumor-invasive growth and chemoresistance via PI3K/Akt/mTOR signaling pathway." (PMID 34367958, 2021). "We identified a new SEP-encoding overlapping sORF (oORF) on the cell polarity determinant Scribble (SCRIB) that is considered a proto-oncogene with tumor suppressor function in Hippo-YAP/TAZ, MAPK/ERK, and PI3K/Akt/mTOR signaling." (PMID 34535749, 2021). "Tyrosine kinase inhibitors (TKIs): It can inhibit the growth and induce apoptosis of tumor cells by inhibiting the two signal transduction pathways of RAS/RAF/MAPK/ERK and PI3K/AKT/mTOR.." (PMID 35082668, 2021). "Many studies have identified that the PI3K/Akt/mTOR axis is overactive in GBM, which increases tumor resistance to treatment." (PMID 34068110, 2021). "Mounting evidence has indicated that numerous anti-tumor drugs can promote apoptosis and autophagy through the inhibition of AKT/mTOR signaling." (PMID 34093198, 2021). "The protein expression of mTOR and p62 were markedly downregulated, and the protein expression of ATG-7, Beclin-1, and LC3-II/LC3-I were markedly upregulated in the tumor tissues in the QYSL and RAPA groups compared with the model group." (PMID 34093717, 2021). "Mammalian target of rapamycin (mTOR) and PI3K signaling allow tumor cells to grow in a nutrient-deprived environment and to overcome anoikis in anchorage-independent conditions." (PMID 34131655, 2021). "The mTOR inhibitor INK128 is, in fact, able to prevent the formation of spinal cord metastases and to dramatically reduce the primary tumour size." (PMID 33803216, 2021). "This is because the mechanisms underlying TSC involve abnormal upregulation of the mammalian target of rapamycin (mTOR) pathway in patients with TSC and subsequent tumor growth in various organs." (PMID 33784976, 2021). "In conclusion, the present study revealed that ARHGAP25 acted as a tumor suppressor regulating cell growth and suppressed glycolysis through AKT/mTOR signaling in PAAD." (PMID 33994864, 2021). "Subsequently, tumor cells activate a number of signaling pathways to initiate DNA damage repair, including the NF-κB, MAPK, AKT/mTOR, and TGF-β signaling pathways." (PMID 34224316, 2021).
tumor (continued). "Our findings are in line with other studies showing that a protein-restricted diet reduces tumor growth in human and mouse xenograft models by modulating the IGF/mTOR pathway." (PMID 34766923, 2021). "First, we assessed the efficacy of two PI3K/mTOR dual inhibitors, PF-04691502 and PKI-402, to inhibit pAkt and increase apoptosis in NET cell lines (BON and QGP-1) and patient-derived tumor spheroids as single agents or combined with radiotherapy (XRT)." (PMID 34065268, 2021). "To evaluate the patterns of expression of ALDH1 (CSC marker) and p-mTOR in human MEC, we performed immunofluorescence studies in tumor specimens retrieved from patients or in xenograft tumors generated in mice." (PMID 33479203, 2021). "Phosphatase and tensin homolog deleted on chromosome ten (PTEN) is a tumour suppressor, which classically counteracts the PI3K/AKT/mTOR signalling cascade." (PMID 33608983, 2021). "The PI3K/Akt/mTOR is an important signal pathway in HCC carcinogenesis and plays a core role in promoting tumor cell proliferation." (PMID 34513919, 2021). "In our study, we identified SNORA23 as a downstream factor of PI3K/AKT/mTOR signaling and showed that SNORA23 played a tumor suppressor role in HCC." (PMID 33710804, 2021). "Studies on RCC cells have proved that PL could significantly suppress the Akt/mTOR signaling pathway mainly through generating ROS in RCC cells, which subsequently led to cell death and inhibition of critical hallmarks associated with tumor initiation and progression." (PMID 36046754, 2021). "In those studies, inhibition of PI3K/AKT/mTOR induced destabilization of the MYCN oncoprotein and triggered anti-tumor effects 41,42." (PMID 33390782, 2021). "Paired tumor sections from both pre-treatment and post-treatment showed that there was significant upregulation of the PI3KCA, AKT1, and mTOR genes and their corresponding protein levels." (PMID 35582035, 2021). "Downregulation of LINC01419 suppresses tumor growth and promotes autophagy through inactivation of the PI3K/Akt1/mTOR pathway in GC." (PMID 34805143, 2021). "PI3K/AKT/mTOR pathway with a significant role in proliferation, angiogenesis, survival, and differentiation has been shown to modulate GLI activity in normal and tumor cells." (PMID 34203598, 2021). "The immunological effects of targeted therapy have also been documented in HNSCCs where inhibition of the mTOR, VEGF, and CDK pathways have been shown to promote anti-tumor immunity, including the recruitment of T cells." (PMID 33485341, 2021). "Due to its anti-inflammatory and antioxidant properties, apigenin also inhibited tumor promotion of HepG2 HCC through inhibited cell proliferation and induced apoptosis and autophagy via PI3K/AKT/mTOR pathway inhibition." (PMID 34950252, 2021). "Differential expression analysis revealed lower expression of genes in metabolic pathways, mTOR, MYC, and AR pathways in the Castrated group compared to the Intact tumor groups." (PMID 33602919, 2021). "Experimental evidence also supports the role of complement activation in PI3K/AKT/mTOR-mediated and RAS/MAPK-mediated tumor growth." (PMID 34439277, 2021). "In the tumor xenograft experiment, ropivacaine was confirmed to inhibit tumor growth, accompanied by inhibition of the IGF-1 R/PI3K/AKT/mTOR signaling axis." (PMID 34696683, 2021). "To further explore the concrete mechanism on the tumor-inhibiting effects of SCARA5 in CRC, we detected the influences of SCARA5 abnormal expression in PI3K/AKT/mTOR pathway." (PMID 34417976, 2021). "The PI3K/AKT/mTOR and Ras/Raf/ERK pathways play important roles in regulating cystic and tumor cell proliferation and growth." (PMID 33920158, 2021).